SERINC5 (serine incorporator 5)
Diseases named in the same sentence as SERINC5 in open-access papers (continued):
Sharing a sentence is not in itself a finding about the gene and the disease.
infection (continued). "Here we show that SERINC5 inhibits influenza A virus infection by targeting virus-cell membrane fusion at an early step of infection." (PMID 36223419, 2022). "Our data show that ORF7a counteracts SERINC5 at two sites during infection, in the producer cells (by virion exclusion) and in the virions themselves." (PMID 35618710, 2022). "When these SERINC5-knockout cells were exposed to WSN infection, a 10-fold increase in viral titer was detected in the supernatants, which is supported by the increase of viral NP and HA proteins in the infected cells." (PMID 36223419, 2022). "After infection of cells with Sendai virus or treatment with poly (I:C), SERINC5 is recruited to mitochondria, where it is colocalized and interacts with mitochondrial antiviral signaling protein (MAVS), enhancing its polymerization." (PMID 35433679, 2022). "Next, we monitored the delivery of IAV RNA into the cytoplasm by real-time RT-PCR, and observed an increase of IAV RNA in SERINC5-knockout A549 cells 0.5 hours after infection, and a decrease in SERINC5-overexpressing cells." (PMID 36223419, 2022). "Initially, ∆Nef HIV-1 was produced from HEK293T and Jurkat cells in the presence of SERINC5 and its lysine mutants, and viral infectivity was analyzed after infection of HIV-1 luciferase-reporter TZM-bI cells." (PMID 35474067, 2022). "To further confirm the role of ORF7a-mediated counteraction of SERINC5 restriction, we complemented ORF7a in trans in infections with the ΔORF7a virus." (PMID 35618710, 2022). "The results showed that Nef prevented SERINC5 from being incorporated into virus particles, and rescued the infection of HXB2 Env or WSN HA protein pseudotyped virus particles in the presence of SERINC5." (PMID 36223419, 2022). "As infection proceeded, SERINC5 translocated sequentially to early endosome (EEA1), late endosome (Rab7) and lysosome (LAMP1)." (PMID 36223419, 2022). "Nef also enhances HIV-1 infectivity in single-round infection experiments by overcoming the antiviral effects of SERINC5 and SERINC3, though, of the two, SERINC5 is the more potent restriction factor." (PMID 34209034, 2021). "The protein and gene expression of SERINC5 were significantly down-regulated in PK-15 and 3D4/2 cells after infection with CSFV at MOIs of 0.1 and 1 at 24 hpi." (PMID 33013817, 2020). "Nef proteins that efficiently enhanced virion infectivity for TZM-bl cells by counteracting SERINC5 also potently promoted infection of primary CD4+ T cells." (PMID 30125328, 2018). "Therefore, under the environment of infection and immune-response trigger treatment, SERINC5 promotes the production of IFN-I and downstream multiple inflammatory factors." (PMID 39902183, 2024). "Furthermore, we proved that silencing of both svRNAs during the course of infection of Vero E6 cells restores SERINC5 expression and enhances the levels of its direct interacting partner, MAVS, a master protein involved in antiviral response." (PMID 36876111, 2023). "Interestingly, when the levels of SERINC5 mRNA were analyzed, we detected a progressive reduction throughout the infection until extremely low values at 16 hpi in both cell lines, which was inversely correlated with the virus titer." (PMID 36876111, 2023). "Infection from SERINC5+ virions leads to the retention of viral RNA in the nucleus." (PMID 36976020, 2023). "This early time of analysis helped us exclude the effect of SERINC5 on blocking re-infection, which could lead to a reduction of virus proteins over multiple rounds of virus replication." (PMID 37766367, 2023). "Infection from HIV-1 (SERINC5+) upregulates RPL35 and DRAP1 in macrophages." (PMID 36976020, 2023). "Results showed that SERINC5 was located at the plasma membrane at 0 hour post infection." (PMID 36223419, 2022).
infection (continued). "We found that SERINC5 restricted infection of all viral particles regardless of the SARS-CoV-2 variant (Alpha, Beta, Gamma and Delta) from which the S protein was derived." (PMID 35618710, 2022). "CD4 is downregulated in infected cells by the HIV-1 proteins Nef and Vpu, and this prevents superinfection, thus avoiding apoptosis and production of infection-compromised virions, and also reduces sensitivity to inhibition by another restriction factor, SERINC5." (PMID 33322320, 2020). "Sequence analysis of the virus population in plasma confirmed that the substitutions in Nef were retained during acute infection; however, changes were observed by week 24 post-infection that fully restored anti-tetherin activity and partially restored anti-SERINC5 activity." (PMID 32302364, 2020). "Interestingly, in the case of the gGag−F-MLV/AmphoEnv, infection was abrogated for all animals independently of genotype (SERINC5−/−, APOBEC3−/−, and BL/6 mice)." (PMID 32665269, 2020). "Analysis of transcriptional profiles or virion proteomes in the presence or absence of Nef established SERINC3 and SERINC5 as targets of Nef, and identified SERINC5 as having more impact on infection by Nef-deficient HIV-1." (PMID 33322320, 2020). "In these assays, SERINC5’s ability to reduce the infectivity of HIV-1 Δnef particles is associated with its incorporation into virions, which reduces the Env-mediated capacity to fuse with target cells during the next round of infection." (PMID 31597782, 2019). "Finally, we show that endogenous SERINC5 expression in primary human lung cells inhibits infection by ORF4-deficient but not wild-type hCoV-229E." (PMID 42253925, 2026). "Therefore, we investigated the hypothesis that the genome of the virus harbors small RNA regulators of host gene expression, similar to miRNAs, that could be responsible for the reduction of SERINC5 levels during infection." (PMID 36876111, 2023). "Interestingly, a new study demonstrated that SERINC3 and SERINC5 promote innate immune signaling, resulting in increased production of type I IFNs and pro-inflammatory cytokines, thereby inhibiting the infection of HIV-1, vesicular stomatitis virus (VSV), and Zika virus (ZIKV)." (PMID 35433679, 2022). "We asked whether SERINC5 inhibits the infection mediated by IAV envelope protein HA." (PMID 36223419, 2022). "Notably, potent antagonism of SERINC5 enhanced the infectivity of virions produced in pre-activated CD4+ T cells only 2- to 3-fold but had up to 10-fold effects when PBMCs were stimulated several days after infection." (PMID 30125328, 2018). "Upon infection of the fusion reporter line, we find an insignificant difference in the fusion of viral particles (HIV-1 SERINC5+/−)." (PMID 36976020, 2023). "To further test this possible mechanism of inhibition, we transiently transfected A549 cells with SERINC5-mCherry, followed by WSN infection." (PMID 36223419, 2022). "To further determine that SERINC5 inhibits the early steps of WSN infection, we performed the single cycle infection assay using WSN HA and NA pseudotyped ΔEnv/NefG2A-GFP viruses, to infect SERINC5-overexpressing or SERINC5-knockout A549 cell lines." (PMID 36223419, 2022). "The HIV-1 accessory proteins Vif, Vpu, and Nef can promote infection by overcoming the inhibitory effects of the host cell restriction factors APOBEC3G, Tetherin, and SERINC5, respectively." (PMID 34140527, 2021). "The promoter activities of IFNβ, ISRE, and NF-κB increased in SeV-infected cells were transfected with SERINC5, suggesting that SERINC5 promoted type I IFN activation in response to infection with an RNA virus." (PMID 33013817, 2020). "Serine incorporator 5 (SERINC5, SER5) suppresses viral cell-free infection." (PMID 39868869, 2025). "report that SARS-CoV-2 does not alter SERINC5 transcription levels at various post-infection time points in Calu-3 cells." (PMID 39902183, 2024).
infection (continued). "On the other hand, we have observed that the recovery of SERINC5 by anti-svRNA treatment during infection was accompanied by a greater increase in MAVS than that normally induced by SARS-CoV-2 infection alone, thus showing an accumulative effect." (PMID 36876111, 2023). "As MAVS increases during infection, the positive regulation by this SERINC5-independent mechanism apparently prevails over the negative effect of reducing SERINC5 (SERINC5-dependent mechanism)." (PMID 36876111, 2023). "However, during infection in Vero E6 and HEK293T-hACE2 cells, even though SERINC5 levels were reduced by the action of svRNAs, the levels of MAVS did not decrease in parallel." (PMID 36876111, 2023). "SERINC5, IAV NP and HA proteins were detected at 48 h post infection by Western blots." (PMID 36223419, 2022). "293T-hACE2 cells expressing SERINC5 were transfected with or without ORF7a followed by infection with the ΔORF7a virus." (PMID 35618710, 2022). "Infection of macaques with this virus resulted in a significant reduction in acute viremia compared to animals infected with wild-type SIV and the accumulation of sequence changes in nef that restore resistance to tetherin, and to a lesser extent SERINC5." (PMID 32302364, 2020). "Two newly identified svRNAs with predicted binding sites in the 3′-untranslated region (3’-UTR) of the SERINC5 gene were characterized and we found that the expression of both svRNAs during the infection was not dependent on the miRNA pathway proteins Dicer and Argonaute-2." (PMID 36876111, 2023). "Since no viral protein capable of repressing the expression of SERINC5 in host cells was identified, we hypothesized that svRNAs encoded in the SARS-CoV-2 genome could be responsible for this repression during infection." (PMID 36876111, 2023). "Since RPL35 and DRAP1 interact with MCE1 exclusively during HIV-1 (SERINC5+) infection, we evaluated whether the expression levels of these host genes affected the viral RNA capping and found that overexpression of the host genes reduced the viral RNA capping even for HIV-1 (SERINC5−)." (PMID 36976020, 2023). "Infection of cells at a high multiplicity of infection (MOI), however, failed to result in detectable quantities in both SERINC5(iHA) protein species, arguing against Nef-induced degradation of the antiviral factor." (PMID 31597782, 2019).
psychiatric disorder (2 papers, 2021 to 2024). A disorder characterized by behavioral and/or psychological abnormalities, often accompanied by physical symptoms. "Among the 36 duplicated genes, CMYA5, HOMER1, SERINC5 and RasGRF2 genes have been repeatedly associated with SCZ and other psychiatric disorders." (PMID 34946848, 2021).
tumor (1 paper, 2025). "Despite the fact that SERINC5 showed higher expression in tumor as well, it did not determine the prognosis of CESC patients." (PMID 39897034, 2025).
SERINC5 also shares sentences with these, for which no sentence is quoted: agranulocytosis (1 paper); cancer (1); fungal infections (1); ovarian carcinoma (1); viral diseases (1).